USP28 (ubiquitin specific peptidase 28)
Diseases named in the same sentence as USP28 in open-access papers (continued):
Sharing a sentence is not in itself a finding about the gene and the disease.
melanoma (continued). "However, apart from promoting the progression of cancers, some recent studies have revealed that USP28 can participate in the suppression of some cancers involving melanoma." (PMID 36879346, 2023). "One of the most significant findings of our study was that USP28 could serve as a significant predictor of anti-CTLA4 therapy response in melanoma patients." (PMID 37450415, 2023). "Importantly, we found hypermethylation of USP28 was positively associated with higher overall survival in DLBC, GMBLGG, Melanoma, and Metastatic Melanoma cases." (PMID 37450415, 2023). "Notably, melanoma and tumours arising in liver, eye and bone showed weak correlation between USP28 and AKT2‐BRAF, and for thyroid cancer, we observed a negative correlation." (PMID 35364627, 2022). "Importantly, the study indicated that in a proportion of melanoma patients, USP28 was deleted, thereby functioning as a key biomarker for patients' response to the BRAF inhibitor therapy." (PMID 31938050, 2020). "Interestingly, a chemical compound screen identified the Polo Like Kinase 1 (PLK1) inhibitor and RAS mimetic, Rigosertib, as being synthetically lethal with USP28 downregulation in melanoma cells." (PMID 31416288, 2019). "As loss of FBW7/USP28 enhances the expression of all three RAF family members, melanoma cells harbouring mutations in this complex may require the activity of both BRAF and CRAF for tumour progression." (PMID 31416288, 2019). "In light of these observations, we sought to establish whether USP28 expression was inversely correlated with BRAF expression in melanoma patients." (PMID 29880484, 2018). "Importantly, USP28 expression was up-regulated after vemurafenib treatment in all of the BRAF (V600E) melanoma cell lines tested." (PMID 29880484, 2018). "Interestingly, the frequency of coalterations between USP28 and FBW7 is low (0.05%; 2/39) indicating that nearly 13% (37/287) of all melanoma patients contain mutations within the FBW7–USP28 complex." (PMID 29880484, 2018). "In addition, USP28-depleted cells are synthetic lethal with the RAF/PLK1 inhibitor rigosertib, suggesting rigosertib as a potential therapeutic strategy in USP28-depleted melanoma." (PMID 29880484, 2018). "Notably, down-regulation of USP28 correlated with high BRAF levels in 75.4% (52/69) of melanoma tumors compared with 55% (16/29) of tumors which displayed both high USP28 and high BRAF (P = 0.023 and R= −0.18)." (PMID 29880484, 2018). "Similarly, USP28 was shown to be deleted in approximately 5% of all melanomas." (PMID 31416288, 2019). "Importantly, we demonstrate that USP28 is deleted in a proportion of melanoma patients and may act as a biomarker for response to BRAF inhibitor therapy in patients." (PMID 29880484, 2018). "The relationship between USP28 and anti-CTLA4 therapy response in patients with melanoma tumors revealed that low-expression USP28 patients outlived high-expression patients in terms of survival rate and time." (PMID 37450415, 2023). "In a small cohort of melanoma patients, where tumours are predominantly driven by mutant BRAF(V600E), USP28 is genetically lost." (PMID 35364627, 2022). "Immunohistochemical staining of USP28 and BRAF was performed on melanoma tissue microarrays containing cores from 98 individual primary melanomas." (PMID 29880484, 2018). "In melanoma cell lines, USP28 expression is positively regulated after MAPK inhibition, whereby USP28 enhances down-regulation of the MAPK pathway through SCF mediated ligase degradation of RAF family members." (PMID 29880484, 2018). "Additionally, in melanoma, MANOVA identified USP28 as an independent prognostic factor for survival, and a study showed that low expression of USP28 was correlated with poor overall survival." (PMID 36879346, 2023). "In the VanAllen 2015 cohort of melanoma tumors, patients with high USP28 expression responded 10% to anti-CTLA4 therapy, which was significantly lower than the 36.3% response rate observed in low-USP28 expression patients." (PMID 37450415, 2023).
melanoma (continued). "Given the role of USP28 in the regulation of BRAF and pERK, we investigated the possibility that low USP28 might be a relevant factor in melanoma." (PMID 29880484, 2018). "Because USP28 is frequently deleted in melanoma and USP28 depletion leads to BRAF stability and enhanced MAPK kinase in HEK293T cells, we asked if interfering with USP28 expression conferred a similar response in BRAF (V600E) melanoma cell lines." (PMID 29880484, 2018). "Although lack of USP28 expression in melanoma cells has no impact on cell proliferation, it favors both the development of resistance to BRAF/MEK inhibitor combination therapies in vitro and in vivo and the generation of emergent tumor cells in mouse xenograft experiments." (PMID 35884430, 2022).
colorectal cancer (7 papers, 2018 to 2025). A primary or metastatic malignant neoplasm that affects the colon or rectum. "JUN is involved in pathways like Toll-like receptor 3 (TLR3) signaling and prolactin signaling and plays a role in transcriptional activation of USP28 in colorectal cancer." (PMID 40092686, 2025). "For example, USP28 facilitates pancreatic cancer progression through activation of the Wnt/β-catenin pathway via stabilizing FOXM1 USP28 promotes colorectal cancer progression by increasing FOXC1 stability." (PMID 37450415, 2023). "JUN is involved in the transcriptional activation of USP28 in colorectal cancer (CRC) cells by activated KRAS." (PMID 36004808, 2022). "It is also involved in activated KRAS-mediated transcriptional activation of USP28 and binds to the USP28 promoter in colorectal cancer cells." (PMID 29568375, 2018). "Similarly, USP28 also controls intestinal homeostasis and promotes colorectal cancer." (PMID 37450415, 2023). "In colorectal cancer (CRC) cells, JUN is involved in USP28 transcriptional activation." (PMID 40092686, 2025).
gastric cancer (7 papers, 2019 to 2024). A primary or metastatic malignant neoplasm involving the stomach. "Furthermore, a study showed that loss of USP28 resulted in a reduction in N-cadherin mRNA levels and an increase in E-cadherin mRNA levels in gastric cancer cell lines, indicating that USP28 can positively regulate the process of EMT in gastric cancer." (PMID 36879346, 2023). "Especially, USP28 mediates the progression of gastric cancer by inducing intracellular reactive oxygen species (ROS) production 14, indicating that USP28 is an upstream regulator of oxidative stress and may possess potential role in ROS-driven heart diseases." (PMID 39431010, 2024).
hepatocellular carcinoma (7 papers, 2016 to 2026). A malignant tumor that arises from hepatocytes. "However, ectopic expression of miR-363-3p in human hepatocellular carcinoma cell lines causes a decrease in USP28, indicating that USP28, c-Myc and miR-363-3p constitute a negative feedback loop." (PMID 36879346, 2023). "The same study also reports that USP28 expression is reduced in patients with hepatocellular carcinoma when comparing carcinoma with control liver tissue from the same patient, in line with the data from the current study." (PMID 32927708, 2020). "MYC was also found to be destabilized by miR-363-3p through directly targeting and inhibiting USP28 in hepatocellular carcinoma, pointing to a putative role for miR-363-3p in contribution to carcinogenesis and establishment of stemness features." (PMID 27816053, 2016). "Furthermore, miR-363-3p suppresses the proliferation of human hepatocellular carcinoma cells by targeting S1PR1 or USP28." (PMID 33744854, 2021). "To test this hypothesis, we used CRISPR to delete the USP28 gene in a hepatocellular carcinoma (HCC) cell line HLF." (PMID 38227944, 2024). "Furthermore, our molecular biology experiments demonstrated that the expression of USP28 was markedly elevated in clinical hepatocellular carcinoma (HCC) tissues compared to adjacent normal tissues, corroborating the findings obtained through database analysis." (PMID 37450415, 2023). "In particular, lack of USP28 results in an earlier onset and greater tumor burden in a mouse model of chemically (diethylnitrosamine (DEN)) induced hepatocellular carcinoma." (PMID 32927708, 2020).
cardiac hypertrophy (4 papers, 2024 to 2025). "We also revealed that cardiomyocyte-derived USP28 negatively regulates antioxidant responses and promotes cardiac hypertrophy by deubiquitinating Tripartite Motif Containing 21 (TRIM21)." (PMID 40561034, 2025). "We showed that cardiomyocyte USP28 positively correlated with cardiac hypertrophy and USP28 deletion in cardiomyocytes significantly protected hearts from hypertrophy and dysfunction." (PMID 39431010, 2024). "The purpose of this study was to clarify the regulatory role and mechanism of USP28 in cardiac hypertrophy." (PMID 39431010, 2024). "In this study, we found the up-regulation of USP28 in cardiac hypertrophy and its cellular localization of cardiomyocytes." (PMID 39431010, 2024). "Xieet al. reported that USP28 regulates mitochondrial homeostasis via the PPARα-Mfn2 axis and modulates cardiac hypertrophy in diabetic cardiomyopathy." (PMID 39210825, 2024). "To further evaluate the role of cardiomyocyte-derived USP28 in hypertrophic heart failure, we generated another cardiac hypertrophy mouse model with Ang II infusion." (PMID 39431010, 2024). "In this study, through transcriptome and single-cell mRNA sequencing (scRNA-seq), we found that a DUB, ubiquitin-specific peptidase 28 (USP28), is involved in cardiac hypertrophy." (PMID 39431010, 2024). "Using a ROS scavenger NAC, we showed that USP28OE-induced cardiomyocyte hypertrophy was attenuated by NAC, indicating the correlation between USP28-related cardiac hypertrophy and ROS production." (PMID 39431010, 2024). "In this study, USP28CKO reduced TAC- or Ang II-induced cardiac dysfunction and hypertrophy, suggesting the potential of USP28 as a therapeutic target for cardiac hypertrophy." (PMID 39431010, 2024). "We also demonstrated that either cardiomyocyte-specific knockout or pharmacologically inhibition of USP28 significantly protected hearts against pathological cardiac hypertrophy in mice." (PMID 39431010, 2024). "Together, these data indicated that cardiomyocyte USP28 expression is increased in cardiac hypertrophy and may mediate the hypertrophy of cardiomyocytes." (PMID 39431010, 2024). "Here, we examined whether specific inhibition of USP28 has a therapeutic effect on established cardiac hypertrophy induced by TAC." (PMID 39431010, 2024). "Therefore, it is necessary to use highly efficient and specific inhibitor against USP28 in the treatment of myocardial hypertrophy." (PMID 39431010, 2024). "We then examined whether TRIM21 was required for the regulation of USP28 on antioxidant responses and cardiac hypertrophy." (PMID 39431010, 2024). "In cardiovascular disease, USP28 has recently been found to be involved in the regulation of diabetic cardiomyopathy by targeting peroxisome proliferator-activated receptor α (PPARα) 15, while the function of USP28 in cardiac hypertrophy is still unknown." (PMID 39431010, 2024). "Therefore, we speculated that USP28 may use TRIM21 as the crucial substrate in regulating cardiac hypertrophy." (PMID 39431010, 2024). "In this study, we aimed to clarify the regulatory role of a DUB, ubiquitin-specific peptidase 28 (USP28), in cardiac hypertrophy and explore the molecular mechanism behind." (PMID 39431010, 2024). "Collectively, we showed that cardiomyocyte USP28 deubiquitinates and stabilizes TRIM21 to negatively regulate antioxidant response, increasing oxidative stress in cardiomyocytes and promoting cardiac hypertrophy and dysfunction." (PMID 39431010, 2024). "Interestingly, in many cases, USP28 and USP25 play opposite roles in the same disease, such as cardiac hypertrophy, where USP25 is a protective protein 21 but USP28 promotes this disease development." (PMID 39431010, 2024). "Although these substrates have a low association with cardiac hypertrophy and were not present in our LC-MS/MS, we cannot completely rule out that USP28 regulates cardiac hypertrophy through these proteins." (PMID 39431010, 2024).
cardiac hypertrophy (continued). "Cardiomyocyte USP28 deubiquitinates and stabilizes TRIM21 to negatively regulate nuclear factor erythroid 2-related factor 2 (Nrf2) antioxidant response, increasing oxidative stress in cardiomyocytes and promoting cardiac hypertrophy and injury." (PMID 39431010, 2024). "Therefore, we present that USP28 may be a more cardiomyocyte-specific and druggable therapeutic target than TRIM21 for cardiac hypertrophy." (PMID 39431010, 2024).
glioblastoma (4 papers, 2022 to 2025). The most malignant astrocytic tumor (WHO grade IV). "USP28 is similarly overexpressed in glioblastoma, contributing to tumorigenicity through MYC regulation." (PMID 40370434, 2025).
pancreatic cancer (4 papers, 2020 to 2023). "However, the biological function and clinical significance of USP28 in pancreatic cancer (PC) are still unclear." (PMID 34584067, 2021). "Patients with an increased expression of USP28 showed a significantly shortened overall survival in cervix and head‐and‐neck tumours, while expression of ∆Np63 significantly shortened life expectancy in pancreatic cancer." (PMID 32128997, 2020). "In another study, a reduction in G0/G1-phase cells and an increase in S-phase cells were observed in pancreatic cancer cells with ectopic expression of USP28, and this advancement in cell proliferation was mediated by the deubiquitination of Forkhead box M1 (FOXM1), which is induced by USP28." (PMID 36879346, 2023).
squamous cell carcinoma (4 papers, 2021 to 2024). A carcinoma arising from squamous epithelial cells. "In line with our results, inhibition of USP28 destabilized ΔNp63 protein and sensitize squamous cell carcinomas cells for cisplatin treatment." (PMID 38498222, 2024). "Recently, USP28 was shown to be upregulated in squamous cell carcinoma (SCC) where it leads to the deubiquitination and stabilisation of ΔNP63." (PMID 37202505, 2023). "USP28 has been identified as a major oncogenic regulator in squamous cell carcinoma and its genetic deletion or inhibition was shown to block tumour growth in mouse models of LSCC." (PMID 37202505, 2023). "In squamous cell carcinoma, USP28 is strongly expressed and stabilizes the essential squamous transcription factor ΔNp63, together with important oncogenic factors, such as NOTCH1, c-MYC and c-JUN." (PMID 34685632, 2021). "Therefore, the inhibition of USP28 using USP28 small molecule inhibitors is effective in the treatment of cancers, particularly in squamous cell carcinoma." (PMID 38711144, 2024). "Our findings suggest that combinatorial targeting of MVP and USP28 could be a therapeutic strategy for the treatment of squamous cell carcinomas." (PMID 37202505, 2023). "Together, these data indicate that both USP28 and SREBP2 are upregulated in human squamous cell carcinoma, particularly the LSCC subtype." (PMID 37202505, 2023). "To study the consequences of USP28 depletion in squamous cell carcinoma, we generated A431 cells expressing doxycycline-inducible shRNA sequences targeting USP28 (#1 and #2) or non-targeting control (shRenilla)." (PMID 37202505, 2023). "For Squamous Cell Carcinoma (SCC), USP28 function was recently clarified." (PMID 34685632, 2021).
liver cancer (3 papers, 2019 to 2026). An epithelial or non-epithelial malignant neoplasm that arises from the liver. "Mechanistically, USP28 interacts with HEY1 and deubiquitinates its lysine 87 residue, thereby stabilizing HEY1 and enhancing the stem-like properties of liver cancer cells." (PMID 42189121, 2026).
lung adenocarcinoma (2 papers, 2023 to 2026). A carcinoma that arises from the lung and is characterized by the presence of malignant glandular epithelial cells. "Analysis of human tissue microarrays revealed elevated expression of USP28, SREBP2 and MVP enzymes in lung squamous cell carcinoma (LSCC) compared to lung adenocarcinoma (LADC)." (PMID 37202505, 2023). "A pan-cancer analysis revealed a trend toward a negative correlation between USP28 levels and the active form of DYRK2 across different tumor types, with high statistical significance primarily driven by lung adenocarcinoma (LUAD)." (PMID 40858801, 2026).
lung squamous cell carcinoma (2 papers, 2023 to 2025). "USP28 deubiquitinates SREBP2 to regulate mevalonate metabolism and promote the progression of lung squamous cell carcinoma." (PMID 39944823, 2025).
microcephaly (2 papers, 2022 to 2024). A congenital or acquired developmental disorder in which the circumference of the head is smaller than normal for the person's age and sex. "Among the genes related to cerebellar volume in the four substructure GWASs we find genes related to ataxia (PEX7, MRPS27, PTK2), neurodevelopment (YPEL3, CASP6, TRIM11, GNB5) and microcephaly (PDCD6IP, USP28)." (PMID 35546225, 2022).
ovarian clear cell cancer (2 papers, 2018 to 2023). An invasive malignant neoplasm that arises from the ovary and is characterized by a predominance of clear and hobnail malignant epithelial cells. "Thus, deubiquitination of Claspin caused by USP28 contributes to cell cycle arrest, which maintains ovarian clear cell carcinoma cell viability in response to a genotoxic stress." (PMID 36879346, 2023). "A previous study showed that, in ovarian clear cell carcinoma cells with DNA damage, knockdown of USP28 reduced both Claspin and Chk1 levels." (PMID 36879346, 2023).
acute myeloid leukemia (1 paper, 2023). Acute myeloid leukemia (AML) is a group of neoplasms arising from precursor cells committed to the myeloid cell-line differentiation. "Thus, through restraining the ubiquitination and degradation of UCK1, overexpression of USP28 resulted in increased effects of 5’AZA on the apoptotic process in acute myeloid leukemia cells." (PMID 36879346, 2023). "In addition, the results in the intravenous acute myeloid leukemia mouse model showed that the growth of acute myeloid leukemia cells with upregulation of USP28 was suppressed after treatment with 5’-AZA, especially compared with cells without USP28." (PMID 36879346, 2023).
Alzheimer disease (1 paper, 2023). A progressive, neurodegenerative disease characterized by loss of function and death of nerve cells in several areas of the brain leading to loss of cognitive function such as memory and language. "As another deubiquitinase, USP25 can take part in many diseases, not only cancers but also Alzheimer’s disease and antiviral immunity, suggesting that inhibitors of both USP25 and USP28 may influence other biological or pathological processes mediated by the lack of USP25." (PMID 36879346, 2023).
cervical squamous cell carcinoma (1 paper, 2023). A squamous cell carcinoma arising from the cervical epithelium. "Analysis of TCGA data revealed that a set of cholesterol biosynthesis genes showed positive correlation with USP28 expression in cervical squamous cell carcinoma and endocervical adenocarcinoma (CESC), head and neck squamous cell carcinoma (HNSC) as well as in LSCC, but not in normal lung tissue." (PMID 37202505, 2023).
chronic lymphocytic leukemia (1 paper, 2024). "Similarly, USP28 prevents FBXW7 self-degradation in chronic lymphocytic leukemia (CLL), leading to elevated levels of Notch1." (PMID 39749199, 2024).